CTLA4 (cytotoxic T-lymphocyte associated protein 4)
Diseases named in the same sentence as CTLA4 in open-access papers (continued):
Sharing a sentence is not in itself a finding about the gene and the disease.
breast carcinoma (continued). "Employing the spontaneous metastasis mouse model bearing 4T1 mammary carcinoma cells with poor immunogenicity, in contrast to other monotherapy groups, the union of anti-CTLA-4 and local RT has statistical significance in the reduction of in situ tumor volume and lung metastases." (PMID 32992835, 2020). "Moreover, the intracellular expression was generally higher than the surface expression and these data are in line with the literature, confirming the interesting putative role of CTLA-4-related pathway in the breast cancer cell metabolism." (PMID 33096896, 2020). "PD-1, PDL-1, and CTLA-4 antibodies are undergoing studies for the treatment of breast cancer." (PMID 31620363, 2019). "In this work, we find that SOFUSATM delivery of anti-CTLA-4 in an orthotopic 4T1-luc mammary carcinoma murine model results in a greater number of complete responses, significantly reduced tumor growth, and a striking inhibition of distant metastases than when administered systemically." (PMID 31754400, 2019). "CTLA-4 has been implicated in immune dysregulation of various malignancies including esophageal cancer, breast cancer, lung cancer, melanoma, non-melanoma skin cancers, cervical cancers, B-cell chronic lymphocytic leukemia, and non-Hodgkin’s lymphomas." (PMID 29672601, 2018). "Similarly, in a preclinical model of breast cancer, RT followed at least a day later by administration of anti-CTLA-4, improved survival compared to either treatment as monotherapy." (PMID 30360504, 2018). "In a pilot study, the CTLA-4-directed antibody, ipilimumab, versus primary tumor cryoablation versus the combination was explored prior to mastectomy in 19 women with early stage breast cancer." (PMID 29881518, 2018). "In all, more than 52% of the patients with the breast cancers may become clinically eligible for the CTLA-4 immunotherapy." (PMID 29672601, 2018). "There is a significant body of evidence documenting the important contribution by circulating and tumour-infiltrating T effector (CD4+ and CD8+) and regulatory (FOXP3+ and CTLA-4+) cells and NK cells in immune-mediated breast cancer cell death in women with LLABCs undergoing NAC." (PMID 28913366, 2017). "In one previous study, the author found that rs733618 and rs4553808 polymorphisms in CTLA-4 increased the breast cancer risk whereas rs231775 and rs3087243 polymorphisms did not have significant associations with breast cancer risk." (PMID 28097051, 2017). "Moreover, elevated expression of CTLA-4 in breast cancer tissues was related to obvious axillary lymph nodes metastases and higher clinical stage." (PMID 28099147, 2017). "In addition to being FDA approved for melanoma, there are emerging trials regarding CTLA-4 inhibitors for breast cancer." (PMID 28085094, 2017). "In addition, CTLA-4 blockade treatment also directly inhibited proliferation and induced apoptosis of CTLA-4+ breast cancer cells." (PMID 28099147, 2017). "In the present study, we hypothesized that CTLA-4 expressed by breast cancer cells (BCCs) might also interfere with the maturation and function of human DCs in tumor milieu as it did on the Tregs." (PMID 28099147, 2017). "The fact that CTLA-4+BCCs treatment influenced the expression of surface markers during DCs maturation suggested an immune inhibitory mechanism that may be effective in breast cancer." (PMID 28099147, 2017). "This study highlights the clinical application of CTLA-4 blockade therapy in breast cancer." (PMID 28099147, 2017). "Here, we searched our database with ‘CTLA4’ and the results revealed that CTLA4 might be involved in several diseases such as breast carcinoma, cervical cancer, etc.." (PMID 31725860, 2017). "Moreover, 5AZA2 treatment combined with anti-CTLA-4 is synergistic in murine mammary carcinoma TS/A and in mesothelioma AB1 models and results in high CD8+ and CD4+ T cell infiltration." (PMID 27847783, 2016). "In breast cancer there is increased expression of CTLA-4, compared with normal breast tissue." (PMID 27777963, 2016).
breast carcinoma (continued). "Combination of an anti-DEC-205 (dendritic and epithelial cells, 205 kDa)-HER2 (human epidermal growth factor receptor 2) vaccine with a dual agonist antibody directed against OX40 and an antagonist antibody directed against CTLA-4 significantly improved survival in a mammary carcinoma model." (PMID 27827885, 2016). "A clinical trial of CTLA-4 blockade treatment for breast cancer showed that peripheral blood immune status was improved after CTLA-4 blockade in most patients, but good peripheral blood immune responses did not invariably translate into lasting beneficial outcomes." (PMID 25893809, 2015). "Demaria and colleagues tested the effects of CTLA-4 blockade and SRS on breast cancer in mice; they reported that CTLA-4 blockade synergizes with SRS to significantly prolong survival, and that this survival benefit and prevention of distant metastases is largely mediated by CD8 T-cells." (PMID 25268164, 2014). "In addition, patients with higher mRNA level of CTLA-4 had breast cancer with worse features, and spontaneous expression of CD3+CTLA-4+ on peripheral blood of patients with tumors was also significantly higher than that of the controls." (PMID 23861693, 2013). "Recently, an interesting study analyzed the effect of CTLA-4 in breast carcinoma." (PMID 23861693, 2013). "In the studies presented, expansion of CD8 T cells with cytolytic phenotype or function was observed with the combination of ixabepilone and anti-mCTLA-4 mAb in the EMT-6 mammary tumor model as well as with the pairing of etoposide and CTLA-4 blockade in the CT-26 colon carcinoma model." (PMID 23873089, 2013). "The promoter region (-1661 G/A, -658 T/C, -318 T/C) of the CTLA-4 gene may be the causal variants in breast cancer disease, whereas CTLA-4 +49 G/A may participate in the progression of breast cancer." (PMID 17825114, 2007). "In comparison to the other types of breast cancer subtypes, TNBC exhibits a higher ability of infiltration of the immune cells and an elevated tendency for immune checkpoint molecule expression, including cytotoxic T-lymphocyte-associated protein 4 (CTLA-4) and programmed death-ligand 1 (PD-L1)." (PMID 40006021, 2025). "Based on the preclinical investigations and due to the poor efficacy of anti-CTLA-4 monotherapy shown in clinical trials, these therapeutics are further tested in combination with other IC inhibitors, chemotherapy, or radiotherapy to improve the treatment outcome of breast cancer patients." (PMID 40003864, 2025). "Hence, CTLA4 inhibitors can be usefull in dealing with immune tolerance in breast cancer." (PMID 38715072, 2024). "CTLA-4 mAB’s has suboptimal antitumor activity and high toxicity effect of anti-CTLA-4 monotherapy in BC; thus, anti-CTLA-4 combination therapy is being explored as an alternative for breast cancer." (PMID 38956700, 2024). "Breast cancers that express high levels of Endo180 receptor (Mrc2) mRNA, which is expressed in myCAFs, are less sensitive to anti-PD-L1 and anti-CTLA4 ICIs in murine models and in human BC tissues." (PMID 39735530, 2024). "Therefore, our data implied that male patients with breast cancer might be insensitive to the PD1/PDL1 or CTLA4 inhibitors." (PMID 37696831, 2023). "In this regard, we aimed to investigate the correlation of A2AR with PD-1 and CTLA-4 regulatory proteins to identify the potential interplay between these immunological pathways and consequently emphasize the relevance of combined therapy in human breast cancer." (PMID 37753093, 2023). "The objective of this study was to determine the correlation between cytotoxic T lymphocyte-associated protein-4 (CTLA-4) expression in peripheral blood and insulin-like growth factor-1 (IGF-1) serum level as biomarkers for predicting trastuzumab treatment efficacy in HER-2 positive breast cancer." (PMID 38406785, 2023).
breast carcinoma (continued). "Taken together, our study might guide as basis for further translational research and suggest that dual blockade of PD-1 and CTLA-4 might enhance the therapeutic activity when compared to monotherapy in breast cancer, thereby unraveling potential benefit for patients." (PMID 35339889, 2022). "Indeed, in an orthotopic model of breast cancer, the tumour-draining LN-targeted administration of immunotherapeutic agents (anti-CTLA-4 and anti-PD-1) is sufficient to suppress tumour growth to the same level as intratumoural administration and to a higher level than systemic administration." (PMID 36139665, 2022). "However, data generated from melanoma patients receiving SRS and CTLA-4 blockade indicate a higher radionecrosis risk, with no breast-cancer-specific evidence available." (PMID 36612206, 2022). "In addition, FibLnc was positively correlated with tumor mutational load and could predict immunotherapy response in patients with breast cancer receiving anti-PD-1 or anti-CTLA4 therapy." (PMID 36408190, 2022). "Likewise, combination therapy with DS-8201a and anti-CTLA-4 antibody persuaded more prominent antitumor effects compared with monotherapy with each agent in murine HER2-expressing breast cancer cells mainly by enhanced tumor-infiltrating CD4 + and CD8 + T cells in vivo." (PMID 34980128, 2022). "Investigation of Treg subsets in blood and primary tumor biopsies from breast cancer patients demonstrated phenotypic similarity between Treg fraction II in blood, corresponding to activated Tregs, and intratumoral Tregs with high expression of CTLA‐4, TIGIT, and ICOS." (PMID 34165864, 2022). "In particular, elevated levels of sPD-L1 before ICI therapy, such as anti-CTLA-4 or anti-PD-1 blockade, were associated with an increased likelihood of progressive disease and unfavorable survival in different tumor settings, such as renal cell carcinoma, NSCLC, breast cancer and other solid tumors." (PMID 36430974, 2022). "In experiments with dendritic cells transfected with anti-CTLA-4 antibody mRNA, the activity of this immune modulator was associated with the enhancement of antigen-specific cytotoxic T lymphocytes (CTL) responses against breast cancer cells, including MCF-7, MDA-MB-231, and T4D7 cell lines." (PMID 34440813, 2021). "Similarly, curcumin was proposed to potentially enhance anti-CTLA-4 immunotherapy in breast cancer." (PMID 33572626, 2021). "Moreover, in breast cancer models, curcumin decreased the expression of PD-L1 in cancer cells leading to improvement of antitumor efficacy, and thus sensitizing cancer cells to anti-CTLA-4 therapy." (PMID 34885122, 2021). "Furthermore, checkpoint inhibitor genes such as PD-L1, PD-1, and CTLA4 were more enrichment in the immunomodulatory subtype of TNBC and the expression of PD-L1, PD-1, and CTLA4 was positively correlated with eight immune-related hub-genes in the breast cancer dataset of TCGA." (PMID 33042828, 2020). "The researchers studied five related gene models of CTLA-4 and found that gene polymorphism is associated with breast cancer susceptibility, such as CTLA-4 +6230G > A can effectively reduce the risk of homozygous and recessive breast cancer in the Chinese population." (PMID 33033520, 2020). "Altogether, our results indicate that cats presenting HER2-positive or TN normal-like tumors could benefit from immunostimulatory therapies (e.g., anti-PD-L1, anti-CTLA-4) and provide support to the use of spontaneous feline mammary carcinoma as a model for human breast cancer." (PMID 32481540, 2020). "Also, we found that Tregs from luminal breast cancer patients showed a distinct pattern of highly expressed costimulatory and co-inhibitory molecules, including PD-1, CTLA-4, ICOS, GITR, OX40, and CD39, underscoring the value of these molecules as targets for immunomodulation." (PMID 32601304, 2020). "However, comparing with other tumors, studies on CTLA-4 in breast cancer are still immature." (PMID 33033520, 2020).
breast carcinoma (continued). "Moreover, CTLA-4 expressed by breast cancer cells may attenuate CD80/86 DC expression and subsequent restricted maturity can hinder proper CD8+ and Th1 CD4+ effector cells." (PMID 32937885, 2020). "Blockade of one of these checkpoints, cytotoxic T-lymphocyte-associated antigen-4 (CTLA-4) or the programmed cell death 1 (PD-1) receptor, may provide proof of concept for the activity of an immune-modulation approach in the treatment of breast cancer." (PMID 31086100, 2019). "However, CTLA-4 blockade in breast cancer cells could recover DC maturation and cytokine production, elevate antigen-presenting function of DCs, reverse Th1/CTLs response and cytokine secretion." (PMID 28099147, 2017). "This study investigated the safety of administering CTLA-4 and PD-1 immunotherapy in combination with cryoablation or standard care in patients with HER2-negative advanced breast cancer following neoadjuvant chemotherapy." (PMID 38956700, 2024). "First, we tested the anti-tumor effects of the anti-CTLA-4 Ab in mouse models of bladder cancer (MB49), breast cancer (EMT6), colorectal cancer (CT26WT), and liver cancer (Hepa1-6)." (PMID 39106430, 2024). "More research is being conducted to assess the combination of ipilimumab and nivolumab, as well as durvalumab and tremelimumab (an additional CTLA-4 inhibitor), in HER2-positive breast cancer patients." (PMID 39539894, 2024). "In certain mouse tumor models (TS/A and 4T1 breast cancer and MCA38 colon cancer), CTLA-4 blockade and RT have a combined therapeutic effect." (PMID 38349740, 2024). "In an analysis of the TCGA database, mRNA relative expression levels of GZMK (log2(TPM + 1)) were correlated with CTLA4, PD-1, PD-L1, CD48, and CCR7 in patients with breast cancer." (PMID 38833021, 2024). "Immunotherapy, particularly immune checkpoint inhibitors targeting PD-1/PD-L1 or CTLA-4, has shown limited efficacy as monotherapy in HER2-positive breast cancer." (PMID 39062682, 2024). "In murine mammary tumor models, A3 activity induces antitumor adaptive immune responses and sensitizes HER2-driven tumors to anti-CTLA-4 checkpoint inhibition." (PMID 39764440, 2024). "In early-stage breast cancer, high co-expression of TIGIT and other immune checkpoint receptors—including PD-1, CTLA-4, LAG-3, and TIM-3—on tumor-infiltrating lymphocytes correlates with increased disease aggressiveness." (PMID 39717767, 2024). "Our analysis revealed that Plek2 expression levels were indicative of how mouse models of 4T1, T22 (mammary cancer), and CT26 (colorectal carcinoma) responded to immunotherapy treatments targeting PD-L1 and CTLA-4." (PMID 39546161, 2024). "Anti-CTLA-4 antibody was the first ICI to be developed, however, clinical trials of this antibody against high-grade breast cancer are limited." (PMID 37860001, 2023). "In the metastatic breast cancer model, the combination of LSAM-DTX + anti-CTLA-4 resulted in significant decrease in TV and thoracic metastasis and increased T cells, NK cells, and NKT cells in the tumor site and peripheral blood." (PMID 36058988, 2023). "This study aimed to explore the potential of CTLA-4 and IGF-1 as biomarkers for predicting the efficacy of trastuzumab treatment in HER-2-positive breast cancer." (PMID 38406785, 2023). "When compared with normal tissues, CpG islands in the promoter regions of PD-1, CTLA-4, and TIM-3 were significantly hypomethylated in breast cancer." (PMID 36936912, 2023). "An IL-15 antibody that targets the CTLA-4 fusion protein, JK08, is being tested in a phase I/II clinical trial, NCT05620134, in breast cancer patients." (PMID 37860188, 2023). "As a first observation, compared to PD-1 and CTLA-4, A2AR appears as the most highly expressed protein in breast cancer tumors." (PMID 37753093, 2023). "In a study of breast cancer, treatment with the MMP inhibitor enhances the efficacy of the anti-CTLA-4 antibody on cancer metastasis." (PMID 36788565, 2023).
breast carcinoma (continued). "In breast cancer, FAP+ CAFs particularly the ECM-myCAF and TGFβ-myCAF clusters, increase PD-1 and CTLA-4 expression on the surface of CD4+CD25+FOXP3+ Tregs." (PMID 37166418, 2023). "In breast cancer, ECM-related CAFs increase the protein expression of PD-1 and CTLA4 on the surface of CD4+CD25+ T lymphocytes and participate in immunotherapy resistance." (PMID 37199594, 2023). "In a mouse model of breast cancer, treatment with an MCT1/MCT4 inhibitor improved the efficacy of ICIs (anti-PD1 plus anti-CTLA-4)." (PMID 37444501, 2023). "In breast cancer cells, MHC class II expression confers response to ICI, using either combination therapy with anti-PD-1 and anti-Lag-3 or treatment with anti-CTLA-4." (PMID 35565329, 2022). "In breast cancer, the expression of COL11A1 was significantly correlated with the expression of PD-1, PD-L1 and CTLA-4." (PMID 36160004, 2022). "COPS5 is required for TNF-α-mediated PD-L1 stabilization in breast cancer cells and inhibition of COPS5 sensitized cancer cells to anti-CTLA4 therapy." (PMID 36304306, 2022). "Although treatment of HER2-positive tumors with RT and an ICI remains uncommon, RT combined with anti-CTLA-4 and anti-HER2 mAbs increased the disease control rate after 12 weeks in patients with HER2-positive breast cancer and brain metastases." (PMID 35763240, 2022). "Immunotherapy has emerged as a new treatment modality in breast cancer, with immune checkpoint blockade (ICB) to target and block PD-1, PD-L1, and CTLA-4 approved as first-line therapy in metastatic triple-negative breast cancer." (PMID 36467500, 2022). "Similar results were observed against breast cancer, for anti-CTLA-4 siRNA-loaded nanoparticles, which significantly reduced CTLA-4-expressing T cells in tumor cells but also in the spleen, leading to tumor regression and increased survival for mice." (PMID 36365144, 2022). "On immune checkpoint genes in breast cancers, POGLUT2 was positively correlated with CTLA4, CD274, TIGIT, LAG3, and PDCD1." (PMID 36158688, 2022). "Mechanistically, in human breast cancer cell lines, it has also been shown that the cGAS/STING pathway is required for interferon activation induced by combined radiotherapy and anti-CTLA-4 immune checkpoint inhibition." (PMID 36387071, 2022). "Here we use DNA barcoding to track murine mammary cancer cell clones during immunoediting and determine clonal transcriptional profiles that allow immune evasion following anti-PD1 plus anti-CTLA4 immunotherapy." (PMID 36344500, 2022). "In a mouse model of breast cancer, the combination of localized radiotherapy with CTLA-4 blockade for poorly immunogenic metastatic cancers refractory to anti-CTLA-4 monotherapy significantly improved survival." (PMID 33801815, 2021). "An anti-CTLA-4-TβRII studied in a mouse model of breast cancer demonstrated superior activity against tumors compared to single-agent or combination TGF-β antibody and an anti-CTLA-4 antibody." (PMID 34830879, 2021). "On the contrary, we observed that application of anti-CTLA-4 (and PD-1 partially) antibodies into the tumor micro-environment inhibits CD4+ and CD8+ cell activity affecting their interaction with breast cancer cells." (PMID 34440813, 2021). "In line with the current results, high stromal CTLA-4 expression independently predicted prolonged survival in NSCLC cases and breast cancer." (PMID 35047074, 2021). "This will be achieved through ex-vivo activation of DCs and T cells co-cultured with autologous breast cancer cells (BCCs) in the presence of anti-PD1 and anti-CTLA4 monoclonal antibodies." (PMID 37305162, 2021).